IGF2BP3 (insulin like growth factor 2 mRNA binding protein 3)
Diseases named in the same sentence as IGF2BP3 in open-access papers (continued):
Sharing a sentence is not in itself a finding about the gene and the disease.
pancreatic cancer (continued). "IGF2BP3 was first cloned from a pancreatic tumor cDNA screen and was originally designated as KOC (KH-domain containing protein overexpressed in cancer)." (PMID 20178612, 2010). "In pancreatic cancer cytoskeleton staining, scratch assay, and Transwell migration and invasion assays, we found that the migratory and invasive abilities of pancreatic cancer cells, enhanced by IGF2BP3 overexpression, were significantly reduced by EMP1 depletion." (PMID 41285728, 2025). "To further explore the effect of IGF2BP3 on the invasive and metastatic abilities of pancreatic cancer cells, we constructed control, Sh-IGF2BP3 (including two targets: Sh1 and Sh2), vector, and IGF2BP3 pancreatic cancer cell lines for a series of in vivo and in vitro experiments." (PMID 41285728, 2025). "Furthermore, we will explore the regulatory impact of long noncoding RNAs (lncRNAs) in this context, specifically how pancreatic cancer cells modulate the IGF2BP3/c‐Myc/SLC1A5 signaling pathway through EV‐mediated linc‐ZNF25‐1 to enhance Asn uptake by PSCs." (PMID 40041969, 2025). "The development of strategies to modulate the activation of the TGF-β/Smads signaling pathway by targeting the IGF2BP3/EMP1/VASP axis may hold promise to improve the current plight of pancreatic cancer." (PMID 41285728, 2025). "And IGF2BP3/EMP1 axis may be involved in regulating microenvironmental remodeling in pancreatic cancer." (PMID 41285728, 2025). "Besides these, high expression of IGF2BP3 predicted poorer overall survival time by analyzing pancreatic cancer samples from TCGA-PAAD and our center." (PMID 41285728, 2025). "Besides, we detected the expression of METTL3 and EMP1 in pancreatic cancer samples serially sectioned with IGF2BP3 in Cohort1 and found that EMP1 was also positively correlated with METTL3 and IGF2BP3." (PMID 41285728, 2025). "Also, IGF2BP3 promoted pancreatic carcinoma cell proliferation and migration by improving B3GNT6 mRNA stability." (PMID 39014364, 2024). "In addition to pancreatic cancers, IGF2BP3 is highly expressed in various cancers including lung, liver, breast, skin, and colon." (PMID 37582618, 2023). "IGF2BP3 was originally reported as a highly expressed gene in pancreatic cancer." (PMID 37298373, 2023). "Additionally, the GEPIA online prediction website showed that the expression of IGF2BP3 mRNA in pancreatic cancer was positively correlated with the expression of SMS." (PMID 36276112, 2022). "Another group demonstrated that IGF2BP3 and IGF2BP3-bound transcripts were localized in cytoplasmic RNA granules, and IGF2BP3 promoted pancreatic cancer cell migration and invasion by regulating the localized translation of IGF2BP3 target transcripts in cell protrusions." (PMID 34239358, 2021). "Furthermore, we performed a prognostic analysis of IGF2BP1, IGF2BP2, and IGF2BP3 in pancreatic cancer with the LinkedOmics and GEPIA datasets." (PMID 33246429, 2020). "However, the expression levels of IGF2BP2 and IGF2BP3 were higher in pancreatic cancer tissue than in normal pancreatic tissue." (PMID 33246429, 2020). "IGF2BP3 was first identified due to its high abundance in pancreatic carcinoma." (PMID 32648571, 2020). "IGF2BP3 was first discovered in this role because of its high expression in pancreatic carcinoma." (PMID 32121275, 2020). "KIF20A may promote the motility and invasiveness of cancer cells by transporting the RNA-binding protein IGF2BP3 and its transcripts towards the cell protrusions along microtubules, as shown in pancreatic cancer cells." (PMID 27941992, 2016). "Nude mice were injected with control-RNAi S2-013 cells, and cytoplasmic granules containing IGF2BP3 were evident in the penumbra of each primary pancreatic tumor taken from such a mouse; moreover, ARF6 was enriched near cell membranes in the penumbra of each tumor." (PMID 25216519, 2014).
pancreatic cancer (continued). "Further data suggest that IGF2BP3 might facilitate pancreatic cancer cell invasion and metastasis through additional mechanisms, including the regulation of localized translation at cell protrusions, altered adhesion by controlling CD44 expression or by stabilizing the SMS mRNA." (PMID 40427100, 2025). "Therefore, we further explored the role of METTL3 and IGF2BP3 on pancreatic cancer cell." (PMID 36276112, 2022). "Therefore, we speculate that METTL3 can regulate SMS mRNA m6A methylation and be recognized by IGF2BP3 to further affect the prognosis of pancreatic cancer." (PMID 36276112, 2022). "Therefore, the highly expressed SMS protein in pancreatic cancer may be related to the expression of METTL3 and IGF2BP3, and the expression of METTL3 and IGF2BP3 related to the migration and invasion of pancreatic cancer." (PMID 36276112, 2022). "Based on lncRNA sequencing data of EVs, we confirmed that EVs derived from pancreatic cancer cells mediate the movement of linc‐ZNF25‐1 into PSCs and promote the uptake of Asn through the IGF2BP3/c‐Myc/SLC1A5 pathway." (PMID 40041969, 2025). "Subsequently, we analyzed the correlation among METTL3 and IGF2BP3 and EMP1 in the pancreatic cancer single-cell dataset." (PMID 41285728, 2025). "First, we quantified the expression of EMP1, IGF2BP3 and METTL3 in cell subpopulations of pancreatic cancer by analyzing single-cell sequencing data." (PMID 41285728, 2025). "Subsequently, infiltration-positive cells were analyzed according to the occurrence of local tissue invasion, METTL3, IGF2BP3 and EMP1 expression levels in pancreatic cancer." (PMID 41285728, 2025). "First, we observed that local invasion, METTL3, IGF2BP3 and EMP1 expression levels influence cell infiltration in the pancreatic cancer microenvironment." (PMID 41285728, 2025). "The m6A reader IGF2BP3 binds to these sites and stabilizes EMP1 mRNA, enhancing its expression in pancreatic cancer." (PMID 41285728, 2025). "We further explored the role of METTL3, IGF2BP3 and EMP1 in the regulation of the tumor microenvironment in pancreatic cancer." (PMID 41285728, 2025). "We found that local tissue invasion and the level of IGF2BP3 and EMP1 affected the immune cell infiltration in pancreatic cancer by multiple immunofluorescence staining." (PMID 41285728, 2025). "Studies have shown that IGF2BP3, ALB, KRT6A, and REG3 partake in the pancreatic cancer origin and development." (PMID 37505298, 2024). "IGF2BP3, also known as IMP3, was first discovered because of its high expression in pancreatic cancer." (PMID 37743642, 2023). "As the stabilizers of m6A methylation, IGF2BP2 and IGF2BP3 can enhance the stability of B3GNT6 and spermine synthase (SMS) mRNA and protein expression, respectively, to promote the progression of pancreatic cancer." (PMID 36981005, 2023). "Knockdown of METTL3 or IGF2BP3 significantly reduced the SMS protein expression and inhibited the migration of pancreatic cancer." (PMID 36276112, 2022). "Survival analysis showed that the expression of METTL3 and IGF2BP3 affected the prognosis of pancreatic cancer patients and that high expression of METTLE/IGF2BP3 can promote the progression of pancreatic cancer." (PMID 36276112, 2022). "In the oncomine database, expression of KIAA1429, LRPPRC, IGF2BP2, IGF2BP3, and EIF3H was higher in pancreatic cancer than normal tissues." (PMID 34332578, 2021). "An m6Ascore based on the expression of IGF2BP2, IGF2BP3, KIAA1429, METTL3, EIF3H and LRPPRC is proposed as an indicator of TME status and is instrumental in predicting the prognosis of pancreatic cancer patients." (PMID 34332578, 2021). "As expected, IGF2BP2 and IGF2BP3 proteins were significantly increased in pancreatic cancer cells compared with HPDE6-C7 cells, while the expression of IGF2BP2 and IGF2BP3 in pancreatic cancer cells was further increased." (PMID 33246429, 2020).
pancreatic cancer (continued). "The growth rates of pancreatic cancer cell lines transfected with IGF2BP2 siRNA and IGF2BP3 siRNA were significantly slower than that of cell lines transfected with the NC siRNA." (PMID 33246429, 2020). "IGF2BP3 (p<0.0001), HOXB7 (p<0.0001), and NEK2 (p<0.0001) mRNA expression levels were significantly increased in patients with cholangiocarcinoma or pancreatic cancer." (PMID 22879911, 2012). "METTL3 regulated m6A modification, and IGF2BP3 recognized the 3’UTR region of EMP1 mRNA, which could be eliminated by silencing METTL3 in pancreatic cancer cells." (PMID 41285728, 2025). "We found that the IGF2BP3 expression was significantly elevated in pancreatic cancer compared with non-cancerous tissue." (PMID 41285728, 2025). "The Compared with adjacent non-tumorous tissues, we found a higher level of EIF3H, IGF2BP2, IGF2BP3, KIAA1429 in all six pancreatic tumor tissues, LRPPRC was overexpressed in five pancreatic tumor tissues, while the expression of METTL3 decreased in four pancreatic tumor tissues." (PMID 34332578, 2021). "In the GSE62452 dataset, we found a high expression of IGF2BP2 and IGF2BP3 in pancreatic tumor tissues compared with adjacent non-tumor tissue." (PMID 34332578, 2021). "Cox’s proportional hazards model was applied to analyse related factors that may affect the overall survival of pancreatic cancer patients, in which IGF2BP2 and IGF2BP3 were identified as independent prognostic factors." (PMID 33246429, 2020). "The KH3-4 domain of the m6A reader proteins IGF2BP2 and IGF2BP3 specifically recognised the m6A-modified YAP1 transcripts, thereby stabilising YAP1 mRNA and increasing YAP1 protein expression, which in turn promoted colony formation and invasion in pancreatic cancer cells." (PMID 42231052, 2026). "Moreover, IGF2BP3 expression was significantly higher in pancreatic cancer tissues with localized tissue invasion than samples without localized invasion." (PMID 41285728, 2025). "Based on the existing literature and our experimental results, we hypothesized that KRT7 and KRT19 are involved in EMT as epithelial components, while CXCL5 and IGF2BP3 act as regulatory factors to regulate EMT, thereby promoting the invasion and metastasis of pancreatic cancer." (PMID 37371833, 2023). "Finally, regarding the SMS regulation mechanism, we verified that the METTL3-IGF2BP3-axis could promote the migration and invasion of pancreatic cancer and that METTL3 and IGF2BP3 further increased the stability of SMS mRNA by modifying SMS mRNA by m6A." (PMID 36276112, 2022). "Therefore, METTL3 and IGF2BP3 may play key roles in the m6A modification of SMS and pancreatic cancer progression." (PMID 36276112, 2022). "Furthermore, pancreatic cancer patients with lower METTL3, METTL14, RBMX, FTO, ALKBH5, YTHDF1, and YTHDC1 mRNA expression levels or higher VIRMA, HNRNPA2B1, EIF3A, IGF2BP1, IGF2BP2, and IGF2BP3 mRNA expression levels had significantly poorer OS (P < 0.05)." (PMID 34330301, 2021). "In addition, recent reports have demonstrated high levels of IGF2BP3 mRNA transcript and protein in pancreatic cancer tissues but not in benign lesions of the pancreas, chronic pancreatitis and/or normal pancreatic tissues." (PMID 20178612, 2010). "Furthermore, 5% of thyroid tumors and 25% of pancreatic cancers hold a specific balanced chromosomal translocation between the IGF2BP3 chromosomal locus on 7p15.3 and the actively transcribed THADA locus on 2p21, which results in the strong overexpression of IGF2BP3." (PMID 32010687, 2019). "The IGF2BP1 mRNA expression level was not upregulated in pancreatic cancer, but the IGF2BP2 and IGF2BP3 mRNA expression levels were upregulated in pancreatic cancer to varying degrees." (PMID 33246429, 2020).
colon cancer (43 papers, 2015 to 2025). "To delve deeper into the underlying mechanisms through which IGF2BP3 governs ferroptosis in colon cancer cell, we performed transcriptomic sequencing on three pairs of negative control and IGF2BP3 KD cells." (PMID 40530014, 2025). "The data obtained from our study suggest that IGF2BP3 is upregulated in colon cancer tissue samples and is associated with unfavorable clinical prognostic indicators." (PMID 40530014, 2025). "Together, the collected evidence indicates that IGF2BP3 deficiency increases the vulnerability of colon cancer cells to ferroptosis." (PMID 40530014, 2025). "The upregulation of IGF2BP3 is associated with poor OS and an advanced stage of colon cancer, suggesting that IGF2BP3 can serve as a prognostic biomarker." (PMID 37965577, 2023). "IGF2BP3 expression is elevated in colon cancers and was shown to be associated with increased tumor angiogenesis, growth, and poor prognosis." (PMID 37582618, 2023). "In pan-cancer Overall Survival (OS) analysis (Kaplan-Meier analysis), we found only higher expression of IGF2BP3 was associated with poor OS among all m6A associated enzymes in colon cancer." (PMID 32993738, 2020). "We investigated all m6A regulated enzymes in colon cancer and found only the overexpression of IGF2BP3 was associated with cancer progression and survival based on The Cancer Genome Atlas (TCGA) databases." (PMID 32993738, 2020). "In general, IGF2BP3 was associated with the progression of colon cancer and worked as a biomarker for pan-cancer." (PMID 32993738, 2020). "We also demonstrated the expression of IGF2BP3 was associated with the pathological stage, which indicated IGF2BP3 promoted the progression of colon cancer." (PMID 32993738, 2020). "IGF2BP3, an oncogenic RNA-binding protein, is implicated in colon cancer progression, while its role in ferroptosis regulation remains unclear." (PMID 40530014, 2025). "This study investigates IGF2BP3’s role in ferroptosis regulation and its interplay with miR-98-5p in colon cancer, aiming to identify therapeutic targets for enhancing ferroptosis sensitivity." (PMID 40530014, 2025). "In conclusion, these findings suggest that the suppression of IGF2BP3 in colon cancer cells drives ferroptosis through the modulation of SLC7A11 mRNA stability, consequently increasing the susceptibility to ferroptosis." (PMID 40530014, 2025). "The presented findings bolster the argument that IGF2BP3 is an active participant in the ferroptotic pathway within colon cancer cells." (PMID 40530014, 2025). "Bioinformatics analyses (TCGA, UALCAN, GEPIA) assessed IGF2BP3 expression and prognostic relevance in colon cancer." (PMID 40530014, 2025). "In conclusion, our study reveals that IGF2BP3 regulates ferroptosis in colon cancer cells through SLC7A11, and miR-98-5p modulates ferroptosis in colon cancer cells by interacting with IGF2BP3." (PMID 40530014, 2025). "For instance, IGF2BP1 typically promotes tumor growth in breast and liver cancers, while IGF2BP2 and IGF2BP3 are involved in enhancing the proliferation and metastasis of certain cancers, such as colon cancer." (PMID 40088376, 2025). "IGF2BP3 was significantly upregulated in colon cancer tissues and correlated with advanced T-stage, higher clinical stage, and poor survival (p<0.05)." (PMID 40530014, 2025). "Overall, our results provide strong evidence that miR-98-5p directly binds to the 3′-UTR of IGF2BP3, downregulating its translation, and thereby promoting ferroptosis in colon cancer cells." (PMID 40530014, 2025). "The current investigation seeks to delineate the functions of IGF2BP3 and miR-98-5p in the ferroptotic pathway of colon cancer cells." (PMID 40530014, 2025). "A notable decline in the mRNA expression of SLC7A11 was detected in colon cancer cells following the knockdown of IGF2BP3." (PMID 40530014, 2025).
colon cancer (continued). "Silencing IGF2BP3 in colon cancer cell lines enhances their sensitivity to ferroptosis, an effect that can be reversed by the ferroptosis inhibitor ferrostatin-1." (PMID 40530014, 2025). "Relationship between IGF2BP3 expression and the clinicopathological features in colon cancer patients." (PMID 40530014, 2025). "To elucidate the potential role of IGF2BP3 in the modulation of ferroptosis within colon cancer, we created stable cell lines by employing lentiviral vectors to mediate the knockdown of IGF2BP3 in both HCT116 and DLD-1 cells." (PMID 40530014, 2025). "These cumulative results highlight the increased expression of IGF2BP3 in colon cancer, suggesting a potential link to a less favorable prognosis." (PMID 40530014, 2025). "IGF2BP3 has been reported to be highly expressed in colon cancer and promote cancer cell proliferation by reading m6A modification of CCND1." (PMID 38353724, 2024). "Soon after its discovery, IGF2BP3’s role as an overexpressed family member in tumors like squamous cell carcinoma was clarified, lung cancer, melanoma, colon cancer, liver cancer." (PMID 38725047, 2024). "In summary, RNase I outperformed RNase T1 in the identification of IGF2BP3 targets in colon cancer cells." (PMID 37582618, 2023). "Although previous studies showed that IGF2BP3 promoted the aggressive phenotypes of CRC cells and regulated cell cycle and angiogenesis in colon cancer, the molecular mechanisms of IGF2BP3 in CRC progression and drug resistance remain largely unclear." (PMID 37658049, 2023). "Several mechanisms were suggested for the function of IGF2BP3 in promoting tumorigenesis in colon cancers including regulation of mRNA localization, translation, and stabilization of oncogenic transcripts." (PMID 37582618, 2023). "IGF2BP3 has been proven to be a predictor of colon cancer progression and poor survival, and its overexpression promotes the proliferation, migration, and invasion of colorectal cancer." (PMID 35047058, 2022). "IGF2BP3 is a specific receptor for m6A in colon cancer, and IGF2BP3 promotes DNA replication and angiogenesis, contributing to cancer development." (PMID 36313365, 2022). "In colon cancer cells, the m6A reader IGF2BP3 promotes neovascularization by recognizing and binding to the m6A modification site in VEGF mRNA and promoting its expression." (PMID 35572524, 2022). "Some research has indicated that IGF2BP3 has good prognostic value as a prognostic biomarker for patients with colon cancer." (PMID 35677634, 2022). "Independent prognostic analysis, GSEA analysis, survival analysis, and other bioinformatics methods were used to investigate the mechanism of IGF2BP3 in colon cancer." (PMID 35677634, 2022). "The important value of IGF2BP3 in colon cancer prognosis and treatment was evaluated using a bioinformatics detection system, and we verified findings using clinical tissue specimens." (PMID 35677634, 2022). "High levels of IGF2BP3 were expressed in colon adenocarcinoma (COAD) samples and in human colon cancer tissues, which was associated with poorer overall survival (OS)." (PMID 35677634, 2022). "IGF2BP3 works as a m6A reader and functions as a potential oncogene in many cancer types including colon cancer." (PMID 36497433, 2022). "The m6A reader IGF2BP3 represses angiogenesis in colon cancer by regulating VEGF, thus inhibiting colon cancer angiogenesis." (PMID 35937999, 2022). "The value of insulin-like growth factor 2 mRNA-binding protein 3 (IGF2BP3), an N6-methyladenosine (m6A) RNA methylation regulatory factor, in the prognosis of colon cancer was still unclear." (PMID 35677634, 2022). "In the research on the colon, IGF2BP3 was demonstrated as a predictor of progression and unfavorable prognosis in colon cancer." (PMID 34721530, 2021). "In colon cancer cells, the m6A reader IGF2BP3 recognizes and binds to m6A modification sites in VEGF mRNA and promotes stability and expression." (PMID 34858499, 2021).